XKR7 (XK related 7)
Synonyms: C20orf159; dJ310O13.4
Tractability: Antibody: UniProt places it where antibodies can reach, with medium confidence; UniProt predicts a signal peptide or a membrane-spanning region; its Gene Ontology location is reachable by antibodies, with medium confidence. PROTAC: its protein half-life has been measured.
Gene: Protein-coding gene on chromosome 20 (31,968,151 to 32,003,387, forward strand). Ensembl gene ENSG00000260903.
Subcellular location: Cell membrane
Gene Ontology:
Molecular function: protein binding
Biological process: apoptotic process involved in development; engulfment of apoptotic cell; phosphatidylserine exposure on apoptotic cell surface
Cellular component: plasma membrane; membrane
Genetic constraint (gnomAD): Loss-of-function variants: 11 observed, 31.47 expected, observed/expected ratio (o/e) 0.35, 90% interval 0.22 to 0.58. The upper end of that interval is the gene's LOEUF score, 0.58, which puts it in group 2 of 6, group 1 being the genes least tolerant of losing a copy. Missense variants: 700 observed, 712.35 expected, observed/expected ratio (o/e) 0.98, 90% interval 0.92 to 1.05. Synonymous variants: 341 observed, 324.09 expected, observed/expected ratio (o/e) 1.05, 90% interval 0.96 to 1.15.
Homologues: Orthologues: chimpanzee XKR7 (99% identical), macaque XKR7 (97% identical), dog XKR7 (93% identical), pig XKR7 (92% identical), mouse Xkr7 (91% identical), rabbit XKR7 (79% identical), guinea pig XKR7 (70% identical), tropical clawed frog XKR7 (56% identical). Paralogues in human: XKR6 (49% identical), XKR4 (48% identical), XKR5 (21% identical), XKR8 (21% identical), XKR9 (16% identical).
Diseases named in the same sentence as XKR7 in open-access papers:
XKR7 is named in the same sentence as 1 disease in open-access papers, as found by Europe PMC text mining. Sharing a sentence is not in itself a finding about the gene and the disease.
XKR7 shares sentences with these, for which no sentence is quoted: tumor (1 paper).